ERVMER34-1 (endogenous retrovirus group MER34 member 1, envelope)
Description:
Endogenous envelope proteins originate from retroviral envelope proteins, which mediate receptor recognition and membrane fusion during early infection. Endogenous envelope proteins may have kept, lost or modified their original function during evolution.
Synonyms: HEMO; envMER34
Tractability: Antibody: UniProt places it where antibodies can reach, with high confidence; UniProt predicts a signal peptide or a membrane-spanning region; its Gene Ontology location is reachable by antibodies, with medium confidence. PROTAC: ubiquitination databases record sites on it.
Gene: Protein-coding gene on chromosome 4 (52,722,618 to 52,751,897, reverse strand). Ensembl gene ENSG00000226887.
Subcellular location: Cell membrane (Endogenous retroviral envelope protein HEMO); Secreted (Endogenous retroviral envelope protein HEMO, secreted form)
Subcellular location (Human Protein Atlas): Nucleoplasm; Cytosol; Predicted to be secreted
Gene Ontology:
Cellular component: extracellular region; plasma membrane
Genetic constraint (gnomAD): Loss-of-function variants: 0 observed, 0.57 expected, observed/expected ratio (o/e) 0, 90% interval 0 to 1.82. That is too few expected variants to judge how well the gene tolerates losing a copy. Missense variants: 1 observed, 3.22 expected, observed/expected ratio (o/e) 0.31, 90% interval 0.11 to 1.4. Synonymous variants: 3 observed, 2.25 expected, observed/expected ratio (o/e) 1.33, 90% interval 0.53 to 1.92.
Homologues: Orthologues: chimpanzee ERVMER34-1 (99% identical), macaque ERVMER34-1 (94% identical). Paralogues in human: ERVW-1 (10% identical), ERV3-1 (9% identical), ERVV-2 (9% identical), ERVV-1 (8% identical), ERVFRD-1 (7% identical).
Diseases named in the same sentence as ERVMER34-1 in open-access papers:
ERVMER34-1 is named in the same sentence as 30 diseases in open-access papers, as found by Europe PMC text mining. Sharing a sentence is not in itself a finding about the gene and the disease. The quoted sentences say what the papers report.
colon adenocarcinoma (1 paper, 2022). "Interestingly, it was recently reported that HEMO (ERVMER34‐1) belongs to a gene signature predicting recurrence of colon adenocarcinoma based on the comparison of mRNAs, lincRNA, and miRNA transcriptomic profiles of recurrent and non‐recurrent tumors." (PMID 34318590, 2022).
mesothelioma (1 paper, 2023). A usually malignant and aggressive neoplasm of the mesothelium which is often associated with exposure to asbestos. "One of these, env encoding ERVMER34-1 (also called HEMO), is preferentially translated in mesothelioma cells compared to mesothelial cells, indicating that proteins from ERVs are produced." (PMID 37296931, 2023).
ERVMER34-1 also shares sentences with these, for which no sentence is quoted: endometrial cancer (2 papers); infection (2); tumor (2); adenocarcinoma (1); Alzheimer disease (1); bladder tumors (1); breast tumor (1); cancer (1); cardiovascular disease (1); colorectal adenocarcinoma (1); endometrial tumors (1); endometrioid ovarian adenocarcinoma (1); endometrium (1); endometrium adenocarcinoma (1); endothelial dysfunction (1); head and neck tumors (1); IgA nephropathy (1); kidney disease (1); leptospirosis (1); lung squamous cell carcinoma (1); lupus nephritis (1); membranous glomerulonephritis (1); metastatic tumors (1); multiple sclerosis (1); Neurological disease (1); ovarian serous adenocarcinoma (1); respiratory infections (1); squamous cell carcinoma (1).